HEY1 (hes related family bHLH transcription factor with YRPW motif 1)
Diseases named in the same sentence as HEY1 in open-access papers (continued):
Sharing a sentence is not in itself a finding about the gene and the disease.
cancer (continued). "The level of APH1A, CTBP1, HEY1, HEY2, JAG2, NOTCH4 was significantly higher in cancer samples compared to the control group, while the concentration of DTX1 TLE2, TLE4 was below the detection threshold." (PMID 41463075, 2025). "Downregulation of ST6GAL1 decreases Jagged1, DLL-1, Notch1, Hes1, Hey1, MMPs and VEGF, and suppresses cancer cell proliferation, migration and invasion." (PMID 37256139, 2023). "Consistent with elevated JAG1 in ICC/IDC cancer cells, NOTCH target genes were significantly increased in endothelial cells in clusters 0 (HES1) and 22 (HES1 and HEY1) and SMC (HES4) located the ICC/IDC TME compared to benign prostate." (PMID 36229464, 2022). "In neuronal cells, the cancer-related gene SLIT2 was found to be upregulated, as were six other cancer-related genes (PDGFRA, DDR2, RSPO3, IL6ST, NTRK2, and HEY1) in cardiomyocytes and one cancer-related gene (HSD3B1) in hepatocyte-like cells." (PMID 32127560, 2020). "Our results verified that HEY1 is a specific molecular target of the NOTCH signaling pathway in SACC cells and that its expression in carcinoma is much higher than that in paracarcinoma tissues." (PMID 32025208, 2020). "During the process of dedifferentiation, multiple genes that were demonstrated to be pivotal in cancer stem cell properties were induced, including PDGFRB, NOTCH1, JAG1, HES1, and HEY1 of the Notch signaling, SNAI1 and SNAI217–20." (PMID 29991717, 2018). "Other Notch targets (HEY1, HEY2 and HES4) also exhibited increased transcript levels in cancer cells compared to benign prostate cells, though the differences in expression were less dramatic than that observed for HES6." (PMID 25864518, 2015). "More importantly, the MMP secretion was Notch dependent because inhibition of the Notch effector Hey1 decreased both MMP2 and MMP9, which eventually decreased cancer cell invasion." (PMID 24931473, 2014). "TGF-β was commonly expressed by multiple cell types, including cancer cells, stromal cells and BECs, and its expression was upregulated in metastatic LNs, potentially driving the expression of MGP, FN1, SOX4, PDPN, and HEY1 in LECs." (PMID 41249124, 2025). "We also added a commonly used reference gene in cancer studies, GAPDH, and a randomly selected non-reference gene, HEY1, for a total of 14 pan-cancer candidate reference genes." (PMID 34422018, 2021). "In cancer, HEY1 has been reported to be essential for the transforming growth factor-β-dependent EMT, which is frequently observed in advanced carcinogenesis and is related to several cancer-related pathways." (PMID 32025208, 2020). "Strikingly, we found that up-regulation of HEY1 and down-regulation of PINK both have significant prognostic implications and are closely correlated in human HCC samples, further consolidating the importance of this pathway in cancer." (PMID 31819034, 2019). "We also found a significant negative correlation between HMGA1 and HEY1 in various cancer types, which were not completely overlapping with those where HMGA1 and HEYL anti-correlate." (PMID 29743479, 2018). "In contrast, the expression of HEY1 followed a pattern almost reciprocal to that of PTOV1 and it was significantly stronger in epithelial cells in BPZ and pre-malignant HGPIN compared to cancer and metastasis, confirming the results at the mRNA level." (PMID 24684754, 2014). "One study regarding the integrative genomic analyses of the HES/HEY family presumed that Notch-independent HES1 and 3 transcription occurred in undifferentiated ES cells, and that Notch-dependent HES1 and 5, HEY1 and 2, and HEYL transcription occurred in fetal, adult or cancer tissue." (PMID 23420695, 2013).
cancer (continued). "Specifically, we wanted to study if NaB treatment can reduce HEY1 and its associated genes’ expression within GBM cell lines, and whether or not this reduction could lead to a reversion of cancer phenotypes." (PMID 28574840, 2017). "Analysis revealed overexpression of APH1A, CTBP1, HEY1, HEY2, JAG2, NOTCH4 regardless of the cancer subtype." (PMID 41463075, 2025).
infection (6 papers, 2009 to 2023). The state of being infected such as from the introduction of a foreign agent such as serum, vaccine, antigenic substance or organism. "Supporting this hypothesis, KSHV-infection of all three cell types, BECs, HUVECs and LECs, resulted in upregulation of HEY1." (PMID 22719258, 2012). "HEY1 levels were not reduced to baseline levels in the presence of NOTCH4 siRNA; this may be attributed to a receptor-independent induction of HEY1 as a consequence of the expression of low levels of KSHV ORF50 during primary infection, or due to incomplete knock-down of NOTCH4." (PMID 19816565, 2009). "We validated in two cell-lines (Caco-2 and HT-29) the changes in expression of a number of genes (MT1E, NPPB, NOTCH3, CYP26A1, HEY1 and CYP1A1) found to be differentially expressed using RNAseq following infection with C. concisus UNSWCD or BAA-1457." (PMID 27677841, 2016). "Further, HEY1, a gene involved in EMT, was consistently upregulated in both cell-lines following infection with strain BAA-1457." (PMID 27677841, 2016). "Therefore, the reciprocal regulation between PROX1 and HEY1 adds another layer of complexity to the opposing regulatory circuits of PROX1 expression by IL3Rα and NOTCH upon KSHV-infection." (PMID 22719258, 2012). "Infection with Ad-CMV-Cre resulted in the deletion of Rbpj and the loss of the stimulatory effect of the NOTCH2 gain-of-function on the Notch target genes Hes1, Hey1, and Hey2 (not shown) since RBPJκ is required for their induction by Notch." (PMID 37865314, 2023). "Ad-CMV-Cre, but not Ad-CMV-GFP, infection led to the inversion of the conditional by inversion (COIN) module and expression of the Notch2ΔPEST or Notch2ΔINV mRNA with the consequent induction of Hes1, Hey1, and Hey2 demonstrating activation of Notch signaling." (PMID 37865314, 2023).
adenocarcinoma (2 papers, 2009 to 2015). A common cancer characterized by the presence of malignant glandular cells. "Additionally, Hey1 was up to −10.0-fold repressed in adenocarcinoma." (PMID 19812696, 2009). "However, we could not observe such an induction of Hey1, Hey2 or Id2 in primary human vascular smooth muscle cells from the umbilical artery, HEK293, HeLa or A549 adenocarcinoma cells.This indicates that endothelial cells react much stronger to BMPs in the serum than other cell types and cell lines." (PMID 25799559, 2015).
benign tumors (1 paper, 2018). "It had previously been shown in a limited number of human samples that TrkC expression is associated with favorable outcome in NB and that Hey1 expression is greatly reduced in NB when compared with benign tumors." (PMID 29750782, 2018).
HEY1 also shares sentences with these, for which no sentence is quoted: head and neck squamous cell carcinoma (3 papers); brain tumor (2); sarcoma (2); squamous cell carcinoma (2); acute lymphoblastic leukemia (1); aneurysmal bone cyst (1); Anxiety (1); astrocytoma (1); B-cell lymphoma (1); basal cell carcinoma (1); bladder cancer (1); bladder tumor (1); Cachexia (1); cardiomyopathy (1); Cirrhosis (1); colorectal tumours (1); COVID-19 (1); dementia (1); embryonic carcinoma (1); endometrial cancer (1); endometriosis (1); esophageal squamous cell carcinoma (1); fibrosarcoma (1); glomerular disease (1); idiopathic pulmonary fibrosis (1); intrahepatic cholangiocarcinoma (1); Kaposi's sarcoma (1); kidney cancer (1); leukemia (1); mantle cell lymphoma (1).
A further 17 diseases each share a sentence with HEY1 in 1 paper.